ALOX12 (arachidonate 12-lipoxygenase, 12S type)
Description:
Catalyzes the regio and stereo-specific incorporation of molecular oxygen into free and esterified polyunsaturated fatty acids generating lipid hydroperoxides that can be further reduced to the corresponding hydroxy species. Mainly converts arachidonate ((5Z,8Z,11Z,14Z)-eicosatetraenoate) to the specific bioactive lipid (12S)-hydroperoxyeicosatetraenoate/(12S)-HPETE. Through the production of bioactive lipids like (12S)- HPETE it regulates different biological processes including platelet activation. It can also catalyze the epoxidation of double bonds of polyunsaturated fatty acids such as (14S)-hydroperoxy-docosahexaenoate/(14S)-HPDHA resulting in the formation of (13S,14S)-epoxy-DHA. Furthermore, it may participate in the sequential oxidations of DHA ((4Z,7Z,10Z,13Z,16Z,19Z)-docosahexaenoate) to generate specialized pro-resolving mediators (SPMs) like resolvin D5 ((7S,17S)-diHPDHA) and (7S,14S)-diHPDHA, that actively down-regulate the immune response and have anti-aggregation properties with platelets. An additional function involves a multistep process by which it transforms leukotriene A4/LTA4 into the bioactive lipids lipoxin A4/LXA4 and lipoxin B4/LXB4, both are vasoactive and LXA4 may regulate neutrophil function via occupancy of specific recognition sites. Can also peroxidize linoleate ((9Z,12Z)-octadecadienoate) to (13S)- hydroperoxyoctadecadienoate/ (13S-HPODE) (By similarity). Due to its role in regulating both the expression of the vascular endothelial growth factor (VEGF, an angiogenic factor involved in the survival and metastasis of solid tumors) and the expression of integrin beta-1 (known to affect tumor cell migration and proliferation), it can be regarded as protumorigenic. Important for cell survival, as it may play a role not only in proliferation but also in the prevention of apoptosis in vascular smooth muscle cells.
Synonyms: 12S-LOX; LOG12; 12-LOX
Tractability: Small molecule: an approved drug acts on it; a structure with a bound ligand is known; a high-quality ligand is known; it has a binding pocket of medium quality; it belongs to a druggable protein family. Antibody: its Gene Ontology location is reachable by antibodies, with high confidence. PROTAC: a small molecule that binds it is known.
Target class: Enzyme
Chemical probes: ML127, VLX-1005
Safety:
Unwanted effects reported when the protein is acted on. In parentheses: how it was acted on, where the effect was seen, and who reports it.
adenoma recurrence (source: ClinPGx)
Gene: Protein-coding gene on chromosome 17 (6,996,049 to 7,010,754, forward strand). Ensembl gene ENSG00000108839.
Subcellular location: Cytoplasm, cytosol; Membrane
Subcellular location (Human Protein Atlas): Cytosol
Pathways (Reactome):
Metabolism: Biosynthesis of DHA-derived SPMs; Biosynthesis of DPAn-3-derived maresins; Biosynthesis of DPAn-6 SPMs; Biosynthesis of Lipoxins (LX); Synthesis of 12-eicosatetraenoic acid derivatives; Synthesis of Hepoxilins (HX) and Trioxilins (TrX)
Gene Ontology:
Molecular function: arachidonate 12(S)-lipoxygenase activity; arachidonate 15-lipoxygenase activity; linoleate 13S-lipoxygenase activity; protein binding; hepoxilin-epoxide hydrolase activity; iron ion binding; metal ion binding; oxidoreductase activity, acting on single donors with incorporation of molecular oxygen, incorporation of two atoms of oxygen
Biological process: arachidonate metabolic process; fatty acid oxidation; leukotriene A4 metabolic process; linoleic acid metabolic process; lipid metabolic process; lipoxin A4 biosynthetic process; lipoxin B4 biosynthetic process; lipoxygenase pathway; negative regulation of muscle cell apoptotic process; unsaturated fatty acid metabolic process; establishment of skin barrier; hepoxilin biosynthetic process; negative regulation of platelet aggregation; superoxide anion generation; lipid oxidation; long-chain fatty acid biosynthetic process
Cellular component: cytoplasm; cytosol; extracellular exosome; membrane; sarcolemma
Genetic constraint (gnomAD): Loss-of-function variants: 61 observed, 81.96 expected, observed/expected ratio (o/e) 0.74, 90% interval 0.61 to 0.92. The upper end of that interval is the gene's LOEUF score, 0.92, which puts it in group 3 of 6, group 1 being the genes least tolerant of losing a copy. Missense variants: 695 observed, 822.7 expected, observed/expected ratio (o/e) 0.84, 90% interval 0.79 to 0.9. Synonymous variants: 271 observed, 316.33 expected, observed/expected ratio (o/e) 0.86, 90% interval 0.77 to 0.95.
Homologues: Orthologues: chimpanzee ALOX12 (99% identical), macaque ALOX12 (96% identical), pig ALOX12 (86% identical), mouse Alox12 (86% identical), guinea pig ALOX12 (85% identical), rabbit ALOX12 (85% identical), rat Alox12 (84% identical), zebrafish alox12 (46% identical). Paralogues in human: ALOX15 (65% identical), ALOX5 (42% identical), ALOX15B (39% identical), ALOX12B (38% identical), ALOXE3 (38% identical).
Diseases named in the same sentence as ALOX12 in open-access papers:
ALOX12 is named in the same sentence as 116 diseases in open-access papers, as found by Europe PMC text mining. Sharing a sentence is not in itself a finding about the gene and the disease. The quoted sentences say what the papers report.
breast cancer (16 papers, 2010 to 2024). A primary or metastatic malignant neoplasm involving the breast. "Further investigation revealed an approximately twofold higher relative risk of breast cancer associated with ALOX12 polymorphisms compared to individuals with heterozygous variants." (PMID 38140764, 2024). "Regarding ALOX12, an increased risk of breast cancer was observed in individuals with the ALOX12 polymorphism in their polyunsaturated fat intake; however, no increase in mortality was observed." (PMID 38140764, 2024). "Further, for the four ALOX12-SNPs in LD that showed similar significant associations with overall breast cancer risk among White women, the reduced risk was stronger among post-menopausal women, as shown for rs3840880 (OR: 0.57, 95% CI: 0.40–0.83)." (PMID 34249719, 2021). "A number of these SNPs in COX2, ALOX5, ALOX5AP, and ALOX12 genes were found to be associated with overall breast cancer risk, as well as breast cancer risk in subgroups defined by menopausal and ER status, in either White or Black women." (PMID 34249719, 2021). "The four ALOX12-SNPs that showed significant associations in White women were found to be associated with stronger reduced risk for ER− breast cancer, as shown for rs3840880 (OR: 0.62, 95% CI: 0.40–0.96)." (PMID 34249719, 2021). "This gene has not been specifically related to lung cancer risk, but former studies have reported (i) that hypomethylation at one of its CpG site was associated with inflammation of the airways, and (ii) that ALOX12 expression was upregulated in in breast cancer tissue." (PMID 35595947, 2022). "Four SNPs (rs3840880, rs1126667, rs434473, rs1042357) in the ALOX12 gene were found in high LD (r2 >0.98) in White women and were similarly associated with reduced risk of breast cancer, with a stronger association among postmenopausal women and for ER− cancer." (PMID 34249719, 2021). "Interestingly, an association between ALOX12 polymorphisms and breast cancer, which was modified by ethnicity could be further explored in regards to the relationship with LCn-3 PUFA intake." (PMID 26891335, 2016). "In breast cancer, fructose upregulates ALOX12 and a corresponding increase in 12-HETE, thereby promoting lung metastasis." (PMID 38200154, 2024). "The analysis of the GEPIA dataset revealed that ALOX15, ALOXE3, and HO‐1 exhibited higher expression levels, while ALOX12 showed lower expression levels in breast cancer tissues compared to normal tissues." (PMID 38516826, 2024). "Expression of ALOX12 (platelet-type 12-lipoxygenase) was reported in different types of human tumors, including prostate cancer, colorectal cancer, breast cancer, and lung cancer." (PMID 39596127, 2024). "In terms of the relationship between ALOX12 and the prognosis of cancer, other groups demonstrated that ALOX12 promoted the malignancy and chemoresistance of tumor cells, including breast cancer and colon cancer." (PMID 36851083, 2023). "A recent study showed an upregulation of ALOX12 in breast cancer cell lines and tumor tissues compared to their corresponding normal breast cells and tissues." (PMID 34249719, 2021). "Several studies have shown the involvement of ALOXs in tumour differentiation and progression and increased levels of ALOX12 were observed in breast cancer." (PMID 21629247, 2011). "ALOX12 has been studied in connection with various malignancies, including colorectal cancer, breast cancer, prostate cancer, bladder cancer, and testicular cancer." (PMID 20626912, 2010). "We previously reported that ALOX12 is involved in breast cancer chemoresistance." (PMID 33224971, 2020). "Moreover, high ALOX12 expression in the lymph node metastases of breast cancer patients inversely correlates with metastasis-free survival as well." (PMID 28013338, 2017). "Significant differences were observed in breast cancer tumour staging for ALOX5, ALOXE3, ALOX12, and ATF3 genes." (PMID 38516826, 2024).
breast cancer (continued). "The results revealed that breast cancer tissues exhibited lower expression levels of SAT1, ALOX5, ALOX12, ATF3, ATF4, GPX4 and NFE2L2 compared to normal tissues; conversely, higher expression levels of ALOX15, ALOXE3 and HO‐1 were observed in breast cancer tissues than in normal tissues." (PMID 38516826, 2024).
atherosclerosis (13 papers, 2010 to 2025). A disease characterized by the build-up of fatty material and calcium deposition in the arterial wall resulting in partial or complete occlusion of the arterial lumen. "ALOX12 gene polymorphisms are associated with the development of atherosclerosis, cardiovascular disease, and 12-HETE levels." (PMID 36011386, 2022). "Due to the function of regulating cell migration, platelet aggregation, and tumor cell proliferation, ALOX12 was mainly associated with the occurrence and procession of diseases like atherosclerosis, thrombosis, and tumors." (PMID 35833141, 2022). "ALOX12 has been implicated in pathways such as the polyols, hexosamines, protein kinase C, advanced glycosylation end-products, vasoconstriction, atherosclerosis, inflammation, and OS, as well as in albuminuria in DM2 (rs1126667) and diabetic nephropathy." (PMID 34545296, 2021). "Polymorphisms in ALOX12 have shown to be genetically associated with subclinical atherosclerosis and with biomarkers of disease in families with type 2 diabetes." (PMID 34091768, 2021). "In the cardiovascular system, the disruption of cardiac Alox12/15 attenuates atherosclerosis in apo E-deficient mice and attenuates cardiac inflammation in mice with severe transverse aortic constriction and diabetic cardiomyopathy." (PMID 29772700, 2018). "The TXAS1 (rs41708) SNP and ALOX12 promoter methylation status have been reported as genomic and epigenomic markers related to ischemic strokes and atherosclerosis." (PMID 38902747, 2024). "ALOX12, ALOX5, and ALOX5AP polymorphisms are genetically associated with subclinical atherosclerosis and with disease biomarkers in families with type 2 diabetes." (PMID 36011386, 2022). "The present study established a proof-of-concept for the identification of AIRE1 and ALOX12 as potential epigenetic markers for the development of atherosclerosis." (PMID 32398127, 2020). "ALOX12 activation has also been observed in atherosclerosis, vascular smooth muscle cells, and platelets in the peripheral blood." (PMID 32398127, 2020). "Promoter methylation changes in AIRE1 and ALOX12 occur in atherosclerosis and can be considered as novel epigenetic markers." (PMID 32398127, 2020). "The role of ALOX12 has been characterized in cell migration, proliferation, and platelet aggregation in the context of neoplasia and atherosclerosis." (PMID 31831037, 2019). "The ALOX12, ALOX15, ALOX5, and ALOX5AP genes represent strong candidates for atherosclerosis risk, especially in the context of type 2 diabetes." (PMID 20592751, 2010). "Polymorphisms within ALOX12, ALOX5, and ALOX5AP are genetically associated with subclinical atherosclerosis and with biomarkers of disease in families with type 2 diabetes." (PMID 20592751, 2010). "Furthermore, ALOX12 has an important function in obesity-related complex phenotypes, including hypertension, atherosclerosis, diabetes and insulin secretion, and obesity itself." (PMID 40149853, 2025). "ALOX12 promoter methylation changes in atherosclerosis might function as a new epigenetic indicator." (PMID 35096131, 2022). "Alox12/15 modulates the inflammatory response and is involved in atherosclerosis." (PMID 29772700, 2018). "Comparison of top-scored IPA canonical analysis showed that atherosclerosis signaling may relate to interactions between CLU and proteins encoded by congenital toxoplasmosis susceptibility genes (TGFβ1, COL2A1, ALOX12, NFκB1)." (PMID 28904337, 2017). "Human 12-lipoxygenase (encoded by ALOX12) and 15-lipoxygenase (encoded by ALOX15) have been localized to atherosclerotic plaques, suggesting that 12/15LO activity is involved in the development of atherosclerosis." (PMID 20592751, 2010). "We hypothesize that polymorphisms in ALOX12, ALOX15, ALOX5, and ALOX5AP genes are associated with subclinical atherosclerosis in multiple vascular beds." (PMID 20592751, 2010).
atherosclerosis (continued). "The ALOX12 methylation differences between monocytes and T and B cells suggested that epigenetic alterations in monocytes might be a separate activation mechanism in atherosclerosis development." (PMID 32398127, 2020). "Changes in promoter methylation in ALOX12 and AIRE1 in atherosclerotic plaques indicated epigenetic alterations of the inflammatory reactions developing in atherosclerosis." (PMID 32398127, 2020).
colorectal cancer (8 papers, 2010 to 2024). A primary or metastatic malignant neoplasm that affects the colon or rectum. "One of the ALOX12 SNPs that was associated with differential colorectal polyp prevention activity of aspirin in our study (the intronic SNP rs2920421) has been reported to interact with NSAID use in a case–control study of colorectal cancer risk." (PMID 37756582, 2023). "Genetic variability in arachidonate lipoxygenase (ALOXs), such as the polymorphisms of ALOX12, may influence risk of colorectal cancer." (PMID 34046350, 2021). "ALOX12 might be one of the factors explaining the high risk of colorectal cancer in patients with schizophrenia." (PMID 20626912, 2010). "ALOX12 has been identified a biomarker and therapeutic target in many human malignancies; it is closely linked to the prognosis, tumor proliferation, invasion, and metastasis of colorectal cancer, and its high expression predicts a better immunotherapy response." (PMID 38719775, 2024). "In the study, ALOX12 was found to be up-regulated in colorectal cancer." (PMID 31528237, 2019). "As a result, ALOX5 and ALOX12 were strikingly up-regulated in colorectal polyp, compared with those in colorectal cancer surrounding tissue, while there were no significant change in the expressions of ALOX15 and ALOX15B." (PMID 31528237, 2019). "To confirm whether LXA4-synthesizing enzymes are dysregulated in colorectal cancer, we detected the expressions of ALOX5, ALOX12, ALOX15 and ALOX15B in colorectal cancer tissue." (PMID 31528237, 2019).
diabetes (7 papers, 2016 to 2025). "Abnormal DNA methylation and genetic variation in ALOX12 are associated with various human diseases and pathological phenotypes, such as cardiovascular disease, diabetes, neurodegenerative disease, respiratory disease, cancer, and infection." (PMID 35033072, 2022). "The upregulation of ALOX-12 and increased generation of metabolite of AA, 12-HETE, have been implicated in a wide variety of pathobiological processes, including diabetes, where subclinical inflammation is seen in various tissues." (PMID 35315361, 2022). "Another study checked the association between genetic variants of ALOX5, ALOX12, ALOX12B, and ALOX15, and type-2 diabetes mellitus (T2D), and found that ALOX12 and ALOX12B genetic variants increased susceptibility to T2D development, possibly though alterations in PUFA/ARA metabolism." (PMID 32235564, 2020).
colon cancer (6 papers, 2021 to 2023). "They used multivariate survival analysis and comprehensive prognosis to show that ALOXE3 and ALOX12 were associated with colon cancer OS, the low expression of both is better for the prognosis of COAD, and ALOXE3 combined with ALOX12 may serve as a potential prognostic biomarker for COAD." (PMID 35265525, 2022). "Thus, ALOX12 can be a possible target to regulate risk of colon cancer." (PMID 34046350, 2021). "In the HPA database, we found that the expression of AKR1C1, ALOX12, and CARS1 in colon cancer tissue is higher than normal tissue and the expression of FDFT1 in colon cancer tissue is lower than normal tissue by immunohistochemistry, which is consistent with our results." (PMID 34046350, 2021).
lung carcinoma (6 papers, 2021 to 2024). "In addition, we silenced the mRNA of ALOX12 using shRNAs that caused the knockdown of ALOX12 in human lung carcinoma cells (H1299) and human renal clear cell carcinoma cells (786-O)." (PMID 36517470, 2022). "Overexpression of ALOX12 in lung cancer increases the activities of RhoA and NF-κB, which promotes cell proliferation and migration." (PMID 38719775, 2024). "In lung cancer, overexpression of ALOX12 facilitated cell growth and migration by promoting RhoA and NF-κB activity." (PMID 34291083, 2021).
lymphoma (6 papers, 2021 to 2023). A malignant (clonal) proliferation of B- lymphocytes or T- lymphocytes which involves the lymph nodes, bone marrow and/or extranodal sites. "Loss of one ALOX12 allele or ALOX12 missense mutations is sufficient to accelerate tumorigenesis in lymphoma models." (PMID 37337630, 2023). "ALOX15B and ALOX12 in lymphoma have been reported to have a tumor-suppressive role in promoting murine lymphomas, while ALOX5, the only one not on chromosome 17p, seems to be required at least for some types of leukemia." (PMID 36750552, 2023). "Consistently, we found knockdown Alox12 could drive Myc-overexpressed pre-B cells transformed into lymphoma in recipient mice (data not shown)." (PMID 36750552, 2023).